MIR5047 (microRNA 5047)
Synonyms: hsa-mir-5047
Gene: MicroRNA gene on chromosome 17 (64,501,214 to 64,501,313, reverse strand). Ensembl gene ENSG00000284368.
Homologues: Orthologues: chimpanzee MIR5047 (100% identical), macaque MIR5047 (100% identical).
Diseases named in the same sentence as MIR5047 in open-access papers:
MIR5047 is named in the same sentence as 1 disease in open-access papers, as found by Europe PMC text mining. Sharing a sentence is not in itself a finding about the gene and the disease. The quoted sentences say what the papers report.
adenoma (1 paper, 2016). A neoplasm arising from the epithelium. "The commonly repressed genes in these two adenoma samples include BCL2L11, TP53INP2, HIST1H1C, TRPM6, MIR22HG, and MIR5047." (PMID 27100181, 2016).